AR (androgen receptor)
Diseases named in the same sentence as AR in open-access papers (continued):
Sharing a sentence is not in itself a finding about the gene and the disease.
prostate carcinoma (continued). "Androgen receptor agonist, would be expected to enhance AMPK activity through overexpression of CAMKK255, and provide the basis for the enhanced killing of AR-positive prostate cancer cells by YM155." (PMID 31395901, 2019). "The current literature on the functions of NRs in prostate cancer indicate that DAX1, SHP, RARβ/γ, FXRs, LXRs, VDR, ERβ, ERRβ/γ, and MR can play antioncogenic roles, while PPARγ, RORγ, SF-1, LRH-1, Erα, and GR, as well as AR, can play oncogenic roles." (PMID 31212954, 2019). "The specificity of compounds 14d and 14s for the cell growth inhibition was also tested using AR-negative PC3 prostate cancer cells." (PMID 31370197, 2019). "Here, we show that forced expression of MIIP inhibits the growth of both AR- positive and negative prostate cancer cell lines as well as the corresponding xenograft, while knockdown of MIIP does the opposite." (PMID 31092266, 2019). "In prostate cancer (PCa) cells, LSD1 functions as a major androgen receptor (AR) coactivator." (PMID 31428587, 2019). "Drugs currently used for the management of prostate cancer mostly act as AR antagonists but do not induce AR degradation." (PMID 31431473, 2019). "We assessed the potential effect of SUMO3 modification on AR intracellular localization by immunostaining in AR-negative prostate cancer DU145 cells, and detected the effect of PIAS1/SUMO3 overexpression on AR sumoylation related degradation." (PMID 31752909, 2019). "In this study, we also found that DU-145 as well as PC-3 cells and its derivatives, known as androgen receptor (AR)-negative cells, express IL-7Rα, but not AR-positive prostate cancer cells such as VCaP and LNCaP-LN3 cells." (PMID 31061414, 2019). "Four PDX models of prostate cancer characterized as androgen receptor (AR) positive or negative were imaged." (PMID 30978984, 2019). "Besides, it has been reported that p35 can translocate into the nucleus in prostate cancer cells and possibly regulates nuclear CDK5 and AR activation." (PMID 31395805, 2019). "Because AR activation promotes the expression of CAMKK271, an AMPKα1 activator, it is possible that the synergistic effect of androgen on the killing of prostate cancer cells by YM155 also or alternatively occurs through enhanced activation of AMPKα by elevated levels of CAMKK2 induced by androgen." (PMID 31395901, 2019). "Establishment of immunofluorescence staining for the AR was performed using prostate cancer cell lines LNCaP and DU145 as positive and negative control, respectively." (PMID 31718606, 2019). "In this study, we generated two anti-androgen and castration resistant prostate cancer cell models that do not rely on AR activity for growth despite robust AR expression (AR indifferent)." (PMID 31551480, 2019). "There is one common androgen receptor for the different androgens (T, DHT, etc.), and its function depends on the concentration of the hormone; for instance, downregulation of the receptor was observed in prostate cancer after the deprivation of androgens." (PMID 31100850, 2019). "FRG1 expression levels are reduced in prostate tumor tissue and its expression affects the cell migratory and invasiveness properties of AR negative prostate cancer cell lines." (PMID 30975102, 2019). "Noteworthy, the antiproliferative effect of capsaicin in prostate cancer mediated by AR signaling or metabolism reprogramming has not been addressed yet." (PMID 31671779, 2019). "In prostate cancer, EGR1 is a critical regulator of AR function." (PMID 31116991, 2019). "In prostate cancer, MAGEA11 is an androgen responsive gene and, following exposure of cells to androgens, co-localises to the nucleus with AR, where it functions as an AR co-regulator increasing AR transcriptional activity." (PMID 31256208, 2019).
prostate carcinoma (continued). "We have demonstrated that FKB selectively inhibited the growth of androgen receptor negative, castration resistant prostate cancer cell lines with minimal effects on the growth of normal prostate epithelial and stroma cells." (PMID 30885218, 2019). "In the present study, we explored the effect of kaempferol on cell growth, apoptosis, vasculogenic mimicry, and invasion of different types of prostate cancer cells, and DHT or AR involved in the pathway of kaempferol related to prostate cancer was also investigated." (PMID 31871879, 2019). "C4-2 and CWR22RV1 prostate cancer cells express androgen receptor, but their growth does not depend on androgen, making them appropriate cell models to study CRPC." (PMID 31534497, 2019). "The role of androgen receptor in the regulation of angiogenetic growth factors in prostate cancer were not addressed as our major focus in this study." (PMID 31718684, 2019). "While ERβ’s tumor suppressor activity appears to be ligand dependent, it is androgen independent, because such an activity is detectable in both AR-positive and -negative prostate cancer cells." (PMID 30979864, 2019). "Although previous studies showed that it represses cell proliferation and negatively affects the cyclin B/CDK1 kinase activity and AR transactivation, its role(s) in prostate cancer has not been defined." (PMID 30863497, 2019). "The completely AR-negative PC-3 prostate cancer cell line does not exhibit changes in proliferation, apoptosis, or other endpoints at ENZ doses of 10 μM or up to 40 μM in combination with radiotherapy." (PMID 30933998, 2019). "Low level of AR and PGC1a expression detected in the patient IRS and ORS suggested the possible interaction between them in the hair, an interaction which has been described in the context of prostate cancer." (PMID 31217429, 2019). "The development of CRPC is a critical problem in patients with prostate cancer and there remains an urgent need to identify targets that do not function by activating AR to develop more effective therapies." (PMID 29717114, 2018). "Thus, AR has been the target of androgen deprivation therapy (ADT) for SDC in recent years, similarly to prostate cancer." (PMID 29416736, 2018). "Taken together, upon stimulation of T or E2, AR or ER may form complex with Src kinase, leading to activation of MAPK in prostate cancer cells, breast cancer cells, or other gonadal tissues." (PMID 29765299, 2018). "Despite a potential role for TF in prostate cancer, an analysis of androgen receptor (AR)‐mediated regulation of TF expression has so far not been reported." (PMID 29427323, 2018). "RUNX1 was reported as a target of AR, and its promoter was bound by EZH2 in prostate cancer." (PMID 29921304, 2018). "The authors also showed that inducible knockdown of PRMT5 inhibits growth of AR-positive but not AR-negative prostate cancer cells as well as xenograft tumors in an AR-dependent manner." (PMID 30613353, 2018). "To further explore the molecular mechanism involved in the suppression of AR expression and its signaling in prostate cancer cells mediated by TLX overexpression, we next examined the basal and androgen-stimulated levels of the endogenous AR and PSA in LNCaP-TLX-stable cells." (PMID 29555975, 2018). "We therefore asked whether V-ATPase inhibitors affect HIF-1α expression and stability in prostate cancer cells and whether HIF-1α may link V-ATPase and AR." (PMID 29988966, 2018). "Androgen receptor (AR) (NR3C4, nuclear receptor subfamily 3, group C, gene 4), a member of steroid hormone group of nuclear receptor superfamily, plays an essential role in the development and proliferation of prostate cancer." (PMID 29755968, 2018).
prostate carcinoma (continued). "Interestingly, in prostate cancer, the JAK/STAT3 signaling pathway regulates expression of AR and this correlates with decreased survival." (PMID 29928478, 2018). "In prostate cancer cell lines, it has been observed that the EGCG-dependent reduction of the acetylated androgen receptor (AR) gene might be induced by EGCG reduction in HAT activity." (PMID 30563268, 2018). "Indeed, lower AR expression and attenuated AR signature activity is shown in CRPC tissues, especially in the subset of neuroendocrine prostate cancer (NEPC) and prostate cancer stem-like cells (PCSCs)." (PMID 29555975, 2018). "This direct regulation of T:E fusion by ERRα is independent of AR expression status in prostate cancer cells as evidenced by its transactivation by ERRα in AR-negative NCI-H660 cells." (PMID 30042415, 2018). "Furthermore, co-expression of MDM2 and MDMX increased levels of co-transfected AR-GFP, a hybrid gene under the CMV promoter, indicating that MDM2/MDMX co-expression increases the stability of AR in prostate cancer cells." (PMID 29464071, 2018). "In contrast, myofibroblasts lacking AR expression permit prostate cancer progression, as they do not inhibit cancer cell proliferation or migration and undergo apoptosis when in close contact with the cancer cells." (PMID 29721186, 2018). "Together, our results suggest that the ERRα-mediated direct transactivation of T:E fusion gene would involve minimal or no cross-talk with AR in prostate cancer cells." (PMID 30042415, 2018). "Most prostate carcinomas exhibit deletions (less commonly translocations) on chromosome 21q that activate ETS-family transcription factors, usually via an N-terminal fusion with the androgen receptor (AR)-activated gene TMPRSS2." (PMID 29671777, 2018). "Here we have shown that the outcomes from co-culturing human prostate myofibroblasts and prostate cancer cell lines, either AR-positive or AR-negative, differ between myofibroblasts that express or lack AR, and involve paracrine and direct signalling." (PMID 29721186, 2018). "Recent study showed MCT2 protein overexpression promotes the growth of prostate cancers by epigenetic regulation of MCT2 isoforms and identifies a link between MCT2, Androgen Receptor (AR), ETS-related gene (ERG) and other oncogenic pathways in prostate cancers." (PMID 30041429, 2018). "In prostate cancer, PKC activity is induced after AR inhibition, which could contribute to NF-κB-driven AR independence." (PMID 30158439, 2018). "Given the critical role of AR in castration resistant-prostate cancer (CRPC) progression, promotion of AR degradation may be a promising target for CRPC patient therapy." (PMID 29707137, 2018). "Recurrent SPOP mutants stabilize TRIM24, enhancing AR signaling and promoting tumor growth via binding with the proteins TIP60 and BRD7, which has led to the proposition of TRIM24 as an essential gene for prostate cancer cell proliferation in CRPC." (PMID 29888169, 2018). "The AR transcriptional activity is also positively regulated by ubiquitination via the E3 ligase ring finger 6 (RNF6), which is overexpressed in hormone-refractory human prostate cancer tissue." (PMID 29921791, 2018). "We expect that PROTAC-mediated AR degradation can potentially address a number of AR-dependent mechanisms of drug resistance that are characteristic of castration-resistant prostate cancer but currently not addressed by enzalutamide-mediated inhibition." (PMID 30271980, 2018). "For the AR negative PC3 prostate cancer cell line, established from an aggressive bone metastasis, galeterone was similarly effective in inhibiting cell growth when compared to LNCaP cells." (PMID 29861848, 2018). "In accordance with clinical observation, androgen receptor (AR)-amplified prostate cancer organoids responded efficiently to the AR inhibitor enzalutamide, while AR-negative prostate cancer organoids were irresponsive to this drug." (PMID 30534474, 2018).
prostate carcinoma (continued). "For example, IKKε is a downstream target that is induced by NF-κB and inhibited by AR in prostate cancer cells, and AR-negative prostate cancer cells show constitutive IKKε activation." (PMID 30158439, 2018). "In this subtype of prostate cancers, both AKT and AR signaling are aberrantly activated." (PMID 29523594, 2018). "Glucocorticoid receptor (GR) is emerging as a key driver of prostate cancer (PCa) progression and therapy resistance in the absence of androgen receptor (AR) signaling." (PMID 30305646, 2018). "In prostate cancer cells, PLGA-CUR also suppressed of the expression of AR and nuclear β-catenin." (PMID 29743988, 2018). "To further investigate the PRC1-independent BMI1 function in prostate cancer, we demonstrated that the BMI1-truncated mutant, BMI1ΔRING, which does not contain the RING domain and cannot interact with RING1B, still directly interacts with AR NTD." (PMID 29402932, 2018). "The development of treatment resistance is thought to depend on so-called cancer stem cells, and an AR-negative prostate cancer stem cell population with constitutive NF-κB activity was recently discovered." (PMID 30158439, 2018). "Considering prostate cancer cell types, ACTB/GAPDH and ACTB/HPRT1 are the most suitable reference gene combinations for mRNA analysis, and miR-16/miR-1228-3p and RNU6-2/RNU43 for miRNA analysis in AR+, and AR− and normal cell lines, respectively." (PMID 29386530, 2018). "PSMA contains a carboxypeptidase that is thought to cleave glutamate from vitamin B9, possibly activating the phosphoinositide 3-kinase pathway and promoting prostate cancer growth independent of the androgen receptor (AR) pathway." (PMID 30701023, 2018). "Together, these results suggest that T:E fusion or ERG expression and its downstream ERG-mediated signaling can be positively regulated by ERRα in prostate cancer cells independent of their AR expression status." (PMID 30042415, 2018). "Based on our observation in AR+ prostate cancer cells, however, we conclude that glycolysis is not significantly upregulated by hypoxia due to the negative interplay between AR and HIF1 at the promoter of GPI." (PMID 30478344, 2018). "IL-1β expression is high in AR-negative prostate cancer cells, but IL-1β also represses AR expression and promotes bone metastasis." (PMID 30158439, 2018). "The finding of AR overexpression in GBM in the present study and based on the documented benefit of AR inhibitors in prostate cancer, the effect of AR inhibitors bicalutamide and enzalutamide on the survival of glioma cell lines A172, U87MG and T98G was explored." (PMID 29731997, 2018). "AR is reported to be suppressed by N-Myc in NEPC and the p38MAPK/FOXC2/Zeb1 pathway in prostate cancer stem-like cells (PCSCs), and inhibition of FOXC2 can reduce stem cell properties and restore AR/PSA expression and also sensitivity to docetaxel in DU145 cells." (PMID 29555975, 2018). "It still remains puzzling how these androgen-responsive fusion genes are transcriptionally regulated in androgen-independent or AR-negative prostate cancer cells." (PMID 30042415, 2018). "A number of RhoGEFs are overexpressed in prostate cancer, including Rac1 GEF P-Rex and Vav3 GEF for RhoA, Rac and CDC42, and are responsible for promoting metastasis and castration resistant prostate cancer (CRPC) by regulating androgen receptor (AR) activity." (PMID 30558664, 2018). "To verify that growth inhibition in our previously tested cells was due to the specific disruption of AR signaling, we treated AR-negative PC3 prostate cancer cells with both ARCC-4 and enzalutamide." (PMID 30271980, 2018).
prostate carcinoma (continued). "A recent study suggested that NONOG, a pluripotency transcription factor, reprograms prostatic cancers to become castration resistant by dynamically repressing and engaging the AR/FOXA1 signaling axis." (PMID 29581876, 2018). "In prostate cancer, the androgen receptor decreases the expression of miR-29b which targets both TET2 and 5-hmC; 5-hmC represses FOXA1 activity, while its reduction activates the mTOR pathway and AR of prostate cancer." (PMID 29850477, 2018). "Conversely, PC-3 is an AR-negative cell line that actively expresses NE markers and is thus more comparable to NE prostate carcinoma." (PMID 29983878, 2018). "Here, we showed for the first time that ERRα can transactivate the T:E fusion gene via its direct binding to TMPRSS2 promoter/enhancer in both AR-positive and -negative prostate cancer cells, with further potentiation by its coregulator PGC-1α." (PMID 30042415, 2018). "The role of AR in the generation or progression of SDC has been under investigated; however, AR has recently become a key target of androgen deprivation treatment for this tumor, as with prostate cancer." (PMID 28938615, 2017). "In addition, some AR-positive prostate cancers transdifferentiate during ADT to an AR-negative, neuroendocrine type of prostate cancer (NEPC)." (PMID 29269934, 2017). "Consistently, ERAD was not regulated by androgen in two AR-negative prostate cancer cell lines, PC3 and DU145." (PMID 28091582, 2017). "For example, AR can be activated in the absence of androgens by interleukin-6 (IL-6) in human prostate cancer cells." (PMID 27741511, 2017). "First, we ectopically expressed ARV7 in PC3 cells, an AR-negative prostate cancer cell line, and demonstrated that resveratrol is capable of inhibiting ARV7 transcriptional activity by downregulating ARV7 protein levels." (PMID 28903374, 2017). "RNF6 plays a critical role in prostate cancer progression by regulating AR transcriptional activity as a transcription factor because knockdown of RNF6 abolishes dihydrotestosterone-induced and androgen-independent AR activation." (PMID 28223545, 2017). "To do so, we decided to ectopically express ARV7 in PC3 cells, a prostate cancer cell line expressing neither full-length AR nor ARV7, by transiently transfection of plasmids expressing ARV7." (PMID 28903374, 2017). "We have also reported that prostate cancer cell lines lacking androgen receptor expression exhibit high constitutive IKKε expression and IL-6 secretion." (PMID 27577074, 2017). "Several studies have shown that the Polycomb repressive complex 2 (PRC2) subunit EZH2 and DNMT3a can cooperate for transcriptional repression; while the interaction between AR and EZH2 has recently been shown to be important for regulating genes in prostate cancer development." (PMID 29383141, 2017). "The Cignal XRE and ARE luciferase reporter assays were utilized to determine the activity of AhR and AR signaling pathways in androgen independent (C4-2) prostate cancer cells in the presence and absence of inhibitors." (PMID 28671964, 2017). "This study gave us the opportunity to expand our understanding of SRF’s role in docetaxel resistance, in the context of AR negative and docetaxel resistant PC-3 cells, and clinical tissues from castrate and docetaxel resistant prostate cancer." (PMID 28249598, 2017). "Evaluation of the altered pathways showed that AR, IGF1, IGFBP5 and ETV1 were markedly decreased in the AfA derived cell line compared with CaA cells, and there was a reciprocal regulatory relationship of miR-24/target expression in prostate cancer patients." (PMID 28157714, 2017). "They showed more significant tumor regressions with dual pathway inhibition via Enzalutamide and rapamycin rather than single pathway inhibition in both PTEN null/AR+ prostate cancer cell lines and PTEN null mice." (PMID 28420128, 2017).